AR (androgen receptor)
Diseases named in the same sentence as AR in open-access papers (continued):
Sharing a sentence is not in itself a finding about the gene and the disease.
tumor (continued). "In addition, it is also emerging as an important factor in breast cancer pathology, glioblastoma, and several other types of human malignancies in which AR-signaling facilitates tumor growth." (PMID 40406608, 2025). "AR plays multifaceted roles in regulating cancer cell invasion and metastasis, with effects that vary across tumor types and microenvironments in cell invasion and tumor metastasis." (PMID 41228208, 2025). "Therefore, the decrease in serum androgens achieved by castration or androgen deprivation therapy (ADT) induces tumor regression by targeting AR." (PMID 39980141, 2025). "The AR expression level positively correlates with increasing tumor grade." (PMID 40075208, 2025). "Importantly, we found that, after TMZ-treatment, the ectopic expression of the miRNA signature was able to impair the tumor-sphere forming ability, decrease spheroid frequency, as well as the AR inhibitor ENZ." (PMID 40399259, 2025). "Moreover, as patients with MSPC are poor responders to androgen receptor signaling inhibitors, impairing the emergence of this cell population represents an attractive strategy to prevent tumor progression." (PMID 39865080, 2025). "The binding of testosterone and 5α‐dihydrotestosterone to the androgen receptor (AR) induces tumor growth and progression by AR homodimerization and interaction with accessory proteins and consequent AR binding to the promoter regions of genes involved in cell proliferation and apoptosis evasion." (PMID 39980141, 2025). "Notably, we found a significant and parallel up-regulation of both AR and mTORC1/2 signaling in tumor cells, as evidenced by the higher AR+mTORC1 meta-scores." (PMID 40570057, 2025). "Investigating the combined effects of EHMT2 inhibitors with AR signalling inhibitors could be valuable, potentially enhancing tumour‐cell eradication by targeting both G1/S and M‐phase transitions in CRPC." (PMID 39763034, 2025). "All these observations suggest that in cell models or tumours which express both AR-FL and AR-Vs, by targeting the AR-FL, this may compromise AR-V function." (PMID 41374958, 2025). "Although preclinical data suggested blockage of AR signaling is promising to inhibit proliferation of these tumor cells, less is known about the exact mechanism, and thus it remains a challenge in blocking androgens/AR signaling pathways in therapeutic strategies against non-reproductive cancers." (PMID 41228208, 2025). "AR promotes tumor proliferation and protects tumor cell survival both in vitro and in vivo." (PMID 41281744, 2025). "One consequence of systemic ARPI therapy could be reduced YAP/TEAD activation in tumor cells due to reduced ECM production by AR-positive stromal cells, thereby lowering the threshold for NEPC transition to occur." (PMID 41509338, 2025). "Moreover, enzalutamide inhibits AR activity by blocking the translocation of AR to the nucleus and its subsequent attachment to DNA, which in turn suppresses the transcription of tumor-related genes." (PMID 41465509, 2025). "Future studies should confirm its expression in prostate tissues, assess functional significance, and investigate mechanisms by which VAPB may contribute to tumor growth, such as interactions with androgen receptor signaling or lipid and calcium signaling." (PMID 41462933, 2025). "Additionally, three AR alteration‐positive patients who initially exhibited therapeutic response or stable disease later developed tumor progression with PSA levels exceeding 20 μg/L, coinciding with the emergence of AR alterations." (PMID 40558023, 2025). "The cut-off value used for the positive AR status was >10% tumor cells." (PMID 40150035, 2025). "Thus, indicating that in a subpopulation of patients the activation of this mechanism is the result of tumor extrinsic (microenvironment) and intrinsic (AR signaling) factors." (PMID 40753365, 2025).
tumor (continued). "Furthermore, the immunohistochemical analysis of vulvar adenocarcinomas in humans revealed strong staining for the androgen receptor, emphasizing its importance in tumor classification and possibly in treatment response." (PMID 40286049, 2025). "These growth factor pathway alterations may work alongside AR signaling changes to promote tumor survival despite 177Lu-PSMA-617 therapy." (PMID 41124032, 2025). "After multiple treatment failures, genomic analyses of tissue and liquid biopsies revealed dynamic changes in tumor biology and the emergence of resistance mechanisms, particularly AR amplification, identified with a liquid biopsy test and validated by [18F]-FDHT PET scan." (PMID 40806723, 2025). "Although speculative, SARMs may represent a new class of agents that selectively inhibit AR signaling in tumor tissue while limiting systemic toxicity." (PMID 40940929, 2025). "While AR expression may influence tumor characteristics, its direct impact on prognosis is still under investigation and this study contributes valuable insights into the role of AR in TNBC prognosis within our cohort." (PMID 40150035, 2025). "Additionally, CDC25B can enhance the activation of estrogen receptor, androgen receptor (AR), and progesterone receptor, thereby promoting tumor malignancy." (PMID 40216745, 2025). "In addition, loss of the chromatin-remodeling protein CHD1, in about 20% of tumors, reprograms the AR cistrome into an oncogenic state and contributes to tumor progression." (PMID 40840524, 2025). "Although associations with clinical outcomes were not identified — likely due to small sample size and retrospective analysis — their findings raise critical questions about the interplay between tumor heterogeneity, genomic background, AR– phenotypes, and metastatic potential." (PMID 40759566, 2025). "183-A is an AR+ tumor derived from a treatment-naive patient, and 118b is an AR- CRPC." (PMID 40753365, 2025). "In fact, OB-related leptin resistance and elevated inflammatory cytokines may amplify prolactin secretion, enhancing AR signaling and tumor progression." (PMID 39910005, 2025). "We hypothesize that the tumor-suppressive effect of AR (e.g., inhibiting ER signaling) is distinct from its DNA repair functions, which are amplified by BQ overexpression." (PMID 40940753, 2025). "The androgen receptor (AR) signaling pathway represents a cornerstone of PCa biology, orchestrating the proliferation and survival of luminal prostate cells and thereby driving tumor initiation and progression." (PMID 40874022, 2025). "In addition to its traditional tumor-promoting effects, studies have also identified that AR possesses tumor suppressor functions." (PMID 40821114, 2025). "This distinction may fundamentally determine the anti‐ or pro‐tumor functions of AR in different cell types, ultimately influencing the immune microenvironment and treatment efficacy." (PMID 40007149, 2025). "This phenomenon suggests that resistance to ADT is not solely dependent on androgen levels but is instead mediated by a range of alternative mechanisms that enable the AR to maintain its function in driving tumor progression, including those driven by oxidative stress." (PMID 40868127, 2025). "In this context, activation of the AR–miR-137–SKI FFL may drive tumor aggressiveness and proliferation, by different mechanisms, including resistance to TGF-β–mediated growth inhibition." (PMID 40862714, 2025). "For example, combining YAP inhibitors with androgen deprivation therapy may effectively suppress AR signaling, inhibit tumor progression, delay the onset of castration resistance, and enhance patient survival and quality of life." (PMID 39963114, 2025). "Of note, in Patient 28, the AR Thr878Ala mutation was also detectable by ddPCR at a very low VAF at the time of treatment initiation, suggesting the early presence of enzalutamide-resistant tumor cells." (PMID 40229848, 2025).
tumor (continued). "Importantly, FOXA1 reprograms the AR cistrome in PCa and its overexpression, either alone or in combination with HOXB13, can push the AR towards a more tumor-like cistrome." (PMID 40833121, 2025). "AR inhibition disrupts the ERα/ERβ balance, reshaping tumor biology." (PMID 40519259, 2025). "Since AR is crucial in hormone-sensitive PCa, studying AR-reactive tumor cell subclusters in PCa samples using scRNA-seq data could enhance our understanding of Enz resistance." (PMID 40849495, 2025). "Similarly, our previous study indicated that areal densities of the putative AR structures positively correlated between the primary tumor and metastasis; however, there was a significantly increased density in nodal metastasis." (PMID 41332218, 2025). "Indeed, our previous study demonstrated that inhibiting Gal-1 expression or function suppressed tumor growth through the inhibition of Akt signaling and AR expression." (PMID 39941722, 2025). "These receptors can reprogram inflammatory transcription, upregulate immune-regulatory mediators, and promote protumor cell–cell interactions beyond tumor epithelial cells, highlighting the existence of a genuine AR–myeloid axis to add to that of tumor epithelial cells." (PMID 41488638, 2025). "As biomarkers such as circulating tumor cells (CTC), DNA repair gene alterations, and androgen receptor splice variants become more widely implemented in clinical practice, ITB and MTB discussions will play a pivotal role in guiding personalized treatment for mCRPC." (PMID 40047924, 2025). "In line with this and also related to androgens signaling, prolactin dysregulation may increase androgen receptor (AR) signaling and tumor growth, posing to the prolactin antagonists as potential adjunct therapy." (PMID 39910005, 2025). "This dual role of ARs complicates their potential as a therapeutic target and suggests that the effects of AR activation may depend on the tumor’s molecular context and the balance between various signaling pathways." (PMID 40286049, 2025). "We therefore propose that AR may be clinically useful as a target to achieve tumor-specific OXPHOS inhibition and FDA-approved anti-AR drugs including enzalutamide and the older generation bicalutamide have been shown to be tolerated in women." (PMID 41216931, 2025). "Our results suggest that assessing AR/ESR1 expression ratios could help predict tumor response and support the use of AR antagonists in cases with elevated ratios." (PMID 40593140, 2025). "These pathways can drive tumor growth independently of AR signaling." (PMID 40008000, 2025). "It is also likely through tumor-promoting miR-224-5p, which targets AR and inhibits AR expression." (PMID 41228208, 2025). "Importantly, ligands that target AR TAD and reduce LLPS also suppress AR transcriptional activity and inhibit tumor growth in vivo." (PMID 40406608, 2025). "Emerging preclinical data suggest that co-targeting hormone receptors (e.g., estrogen receptor α or androgen receptor) alongside immunotherapy could enhance anti-tumor immunity." (PMID 40438106, 2025). "Notably, bone cell activity inversely correlated with tumor AR activity (AR, FOXA1, HOXB13, KLK2, KLK3, NKX3-1, STEAP2, TMPRSS2) and PSA levels." (PMID 40342734, 2025). "In addition to inhibiting the nuclear translocation of AR and its transcriptional activity, it competes to prevent ligand–receptor binding and interferes with AR-DNA interactions, which, in turn, reduces signals that promote tumor proliferation." (PMID 40656519, 2025). "AR acetylation, facilitated by acetyltransferases, such as coactivators p300/PCAF, also serves to promote PC growth, and overexpression of these enzymes has been linked to tumor progression." (PMID 40051495, 2025).
tumor (continued). "Importantly, the pre–AR inhibitor treatment ARPC tumor (2623-1) and post–AR inhibitor treatment DNPC tumor (2623-2) were taken from the same patient, demonstrating that preexisting PROX1-high cells were not present in the pretreatment ARPC tumor we examined." (PMID 40454483, 2025). "In contrast, in castration-resistant prostate cancer (CRPCa), the biological and imaging effects of ADT may differ substantially due to tumour evolution, androgen receptor pathway alterations, and increased heterogeneity." (PMID 41039098, 2025). "Finally, AR-mediated transcription of target genes drives tumor growth and survival, and transcriptional inhibitors aim to suppress this terminal output of AR signaling." (PMID 41228300, 2025). "Regardless, AR may still be a driver for tumor growth and progression, and therefore, a potential target for the therapy." (PMID 40392873, 2025). "This hypothesis was supported by the observation that AR inhibited tumor cell invasion in NSCLC via the circular-SLCO1B7/miR-139-5p axis and reduced oncogene D52 expression." (PMID 41228208, 2025). "Notably, AR signaling remains active even under androgen-deprived conditions in tumor cells, facilitating continued tumor proliferation and the emergence of therapy resistance." (PMID 40747210, 2025). "In addition, MCL1 and BCLXL have been shown to reduce the anti-tumour efficacy of AR targeting therapies and chemotherapies in PCa." (PMID 41438049, 2025). "This promotes tumor cell proliferation and cross-talk between ER and AR signaling pathways." (PMID 41139205, 2025). "Prospective studies that include representative numbers of tumor tissues from different BC subtypes will be highly useful in better defining the potential differentiating role of these ratios in BC, particularly the AR/PGR ratio." (PMID 40593140, 2025). "Most castration-resistant tumours exhibit highly active AR signalling." (PMID 40163908, 2025). "Integrative analyses identify DNA methylation-driven gene links based on location (H3K27ac, H3K27me3, promoters, gene bodies) pointing to mechanisms underlying dysregulation of genes involved in tumor lineage (ASCL1, AR) and therapeutic targets (PSMA, DLL3, STEAP1, B7-H3)." (PMID 40593552, 2025). "Interestingly, AR can exhibit both tumor‐promoting and tumor‐suppressing effects depending on the context." (PMID 40583627, 2025). "Additionally, another study demonstrated that USP22 modulates both the androgen receptor and Myc to drive AR-driven cancer cell proliferation and tumor growth in CRPC cells." (PMID 40771930, 2025). "We demonstrate the response to both testosterone treatment and testosterone withdrawal of these cell lines in vitro and in vivo and illustrate that response is correlated with overall levels of AR expression and the heterogeneity of expression within a tumor population." (PMID 40002188, 2025). "Moreover, AR positivity has been suggested to reflect the metastatic potential of tumor cells in some BC subtypes." (PMID 37902839, 2024). "By following up on the tumour zone of origin, the differential response to treatment in both localised (ie, radical prostatectomy or radiotherapy) and metastatic (ie, androgen receptor signalling inhibitors or chemotherapy) settings may be present." (PMID 39886173, 2024). "In addition, inhibiting menin with MI-503 reduces cell proliferation, colony formation, and tumor xenograft growth in AR-positive cell lines." (PMID 39336822, 2024). "Additionally, AhR controls genes that regulate the cell cycle and apoptosis, influencing tumor growth independently of AR." (PMID 39184676, 2024). "In castration‐resistant PCa, AR is continuously activated to drive tumor progression." (PMID 38501452, 2024). "Further results suggested that supplementing with inosine could significantly reduce tumor NF-κB phosphorylation level and AR transcription and expression level." (PMID 39203495, 2024).
tumor (continued). "In addition, 60% of TNBC samples were classified as basal-like (based on CK5/6 and/or EGFR expression in >10% of tumor cells) and 36% had a molecular apocrine phenotype (based on positive staining for AR and FOXA1 in ≥1% of tumor cells)." (PMID 39723208, 2024). "Moreover, the upregulation of coactivators and androgen-producing enzymes within tumor cells and microenvironment contribute to AR signaling persistence in CRPC." (PMID 39359255, 2024). "As a result, timely discontinuation of drug treatment upon emergence of resistance during AR inhibitor therapy could potentially inhibit tumor growth." (PMID 38859590, 2024). "AR activity was significantly higher in tumor tissues compared to normal tissues from EA men." (PMID 38566104, 2024). "Importantly, in an AR-overexpressing TNBC cell line (MDA-MB-231-AR), SARMs (enobosarm and GTx-027), but not the AR antagonist bicalutamide, reduced cell proliferation and inhibited the in vivo tumor growth of MDA-MB-231-AR xenografts." (PMID 38339092, 2024). "Interestingly, the inhibition of PI3K or mTOR resulted in reduced tumor growth in patient-derived xenograft models of LAR that were resistant to AR antiandrogens." (PMID 38339092, 2024). "However, tumors often become resistant but the AR remains a critical factor for tumor proliferation also for CRPC." (PMID 38902772, 2024). "Because aberrant IGF1 and Wnt activation has been shown to directly induce prostate oncogenesis and PCa development, these findings implicate stromal AR in Gli1-lineage cells acting as tumor niches to support prostate epithelial oncogenesis through IGF1/Wnt activation." (PMID 39369165, 2024). "We next explored the impact of 15 mg/kg once daily intraperitoneally Thio-2 on AR signaling and growth in the tumor-bearing CP50 PDX, to determine whether any therapeutic impact was observed." (PMID 38412481, 2024). "Transcriptional mechanisms of ADT resistance are prominent in PCa, where multiple resistance mechanisms coexist in the same tumor owing to the high heterogeneity of AR expression and of other key PCa drivers, and where the tumor microenvironment acts as another determinant of ADT resistance." (PMID 38546787, 2024). "Moreover, AR expression is increased in TNBC in early metastatic lesions compared to the primary tumor (PT) suggesting that AR supports tumor cell survival metastatic spreads." (PMID 37902839, 2024). "Our data suggest a limited role of AR immunohistochemistry for tumor distinction and a prognostic role in breast and clear cell RCC and highlight tumor entities that might benefit from AR-targeted therapy." (PMID 38790919, 2024). "Understanding whether CK1 can modulate AR activity will be important therapeutically; for example, when considering combination treatments and at what stage of tumour progression this will be most effective." (PMID 39001502, 2024). "For example, the FDA‐approved Olaparib, an inhibitor of pan‐Poly(ADP‐ribose) Polymerase (PARP) in the DDR pathway, has been clinically used for treating Breast Cancer Gene 1/2 (BRCA1/2)‐deficient PCa, making research significant on AR downstream signaling, particularly in the DDR pathway." (PMID 38501452, 2024). "Furthermore, they demonstrated that macrophage density correlated with ADT resistance and that macrophage depletion in mice (using a CSF1 antibody) reduced both tumor androgen levels and various surrogates of AR activation, as well as better outcome after ADT." (PMID 39635522, 2024). "In this study, AR expression was also correlated with various other clinicopathological prognostic factors such as age, tumor size, pT stage, nodal status, histological grade, ER expression, PgR expression, human epidermal growth factor receptor 2 (Her2) status, and molecular subtype." (PMID 39497884, 2024). "Therefore, the AR cistrome was associated with ARE motifs in normal prostate tissue and de-enriched in PCa, suggesting a tumor-suppressive regulatory element." (PMID 39672812, 2024).